PML (PML nuclear body scaffold)
Diseases named in the same sentence as PML in open-access papers (continued):
Sharing a sentence is not in itself a finding about the gene and the disease.
tumor (continued). "PML is involved in wide range of important cellular processes, including tumor suppression, transcriptional regulation, apoptosis, senescence, DNA damage response, and viral defense mechanisms." (PMID 32724039, 2020). "It was intriguing to decipher what roles a stabilized PML hold in regulating tumor suppression via its effector molecules, namely Foxo3a and Survivin." (PMID 31506431, 2019). "Our data demonstrate that PML acts as an important tumor suppressor in HCV‐dependent liver pathology." (PMID 31144474, 2019). "Our data depict a new mechanism determined by the presence of PML/RARa in APL tumor cells involving NRF2." (PMID 31905996, 2019). "This highlights the importance and direct correlation of PML as a tumor suppressor during HCV‐related carcinogenesis." (PMID 31144474, 2019). "Taken together, this study provides further insight into the role of PML fostering a permissive milieu for the liver toward tumor development, as well as supporting HCV‐related HCC development." (PMID 31144474, 2019). "PML, originally identified to be involved in the rise of PML–RARα and RARα–PML fusion proteins, is a well-known tumor suppressor by regulating cell apoptosis and cell cycle." (PMID 31152142, 2019). "PML‐deficiency in combination with HCV therefore is associated with decreased expression of RASSF6, correlating with increased cell proliferation and tumor growth in vivo and in vitro." (PMID 31144474, 2019). "The same study reported that PML protein is also frequently overexpressed in carcinomas of larynx and thyroid, epithelial thymomas, Kaposi’s sarcoma, and in Hodgkin cells, a tumor of cytokine-producing cells." (PMID 29888200, 2018). "In the past decades, a body of in vivo and in vitro studies have elucidated PML’s function in the blockade of cell growth, cell migration and angiogenesis, thus strengthening a role of PML in the tumor suppression." (PMID 29416846, 2018). "Under pro-apoptotic conditions, such as cisplatin and UV treatment, YAP is phosphorylated at the Tyr357 residue, which enhances the transcription of pro-apoptotic genes, such as Bax, p53AIP1, PML, and puma; this supports its function as a tumor suppressor." (PMID 30574018, 2018). "The promyelocytic leukemia protein (PML) is another powerful tumor suppressor but always mutant in cancer." (PMID 30158600, 2018). "Promyelocytic leukemia protein (PML), a component of nuclear domain 10 (ND10), PML oncogenic domain (POD) or PML nuclear bodies (PML-NB), has tumor suppressive and antiviral defense activities." (PMID 30349510, 2018). "We find that this pathway is suppressed by the PML tumor suppressor through sequestration of PP1α into NBs in PTEN-null cells as a result of failsafe mechanisms evoked by PTEN loss." (PMID 29335436, 2018). "The role of PML in tumor suppression has been extensively studied but increasing evidence indicates that PML also plays versatile roles in stem cell renewal, metabolism, inflammatory responses, neural function, mammary development and angiogenesis." (PMID 29416846, 2018). "The tumor suppressor activity of PML was clearly demonstrated based on the higher incidence of tumor formation in Pml knockout mouse models." (PMID 29416846, 2018). "Beside the correlative connection between carcinogenesis and PML expression, there is plenty of experimental evidence for a direct tumor-suppressive role of PML." (PMID 29888200, 2018). "Typical examples included known or putative tumor suppressors, such as NF1, DICER1, PML, PDS5A, MAP3K7, and PPP2R5A, in which SF3B1 mutation resulted in usage of alternative 3′ splice sites." (PMID 30194306, 2018). "A body of evidence indicated that PML possesses tumor suppressing activity by regulating apoptosis, cell cycle, senescence and DNA damage responses." (PMID 29416846, 2018).
tumor (continued). "The tumor suppressor PML, which is localized at the MAMs, represses autophagy by promoting ER–mitochondrial Ca2+ transfer and mitochondrial respiration." (PMID 29491433, 2018). "Since PTEN mono-ubiquitination is a prerequisite for its nuclear retention and tumor suppressor functions, Pml knockout MEFs or PML dysfunction in APL cells results in PTEN de-ubiquitination and nuclear exclusion." (PMID 29416846, 2018). "The frequent deregulation of SCP1 and SCP3 in clear cell renal cell carcinoma and concomitant PML reduction results in mTOR-HIF1 axis activation, thus increasing tumor-associated angiogenesis and tumor burden in Xenograft models." (PMID 29416846, 2018). "Here we report an S6K/PP1α/B-Raf pathway that activates MAPK signaling in PI3K/AKT-driven cancers and is opposed by the promyelocytic leukemia (PML) tumor suppressor." (PMID 29335436, 2018). "The cytosolic PML also likely functions as a tumor suppressor by controlling calcium transfer and autophagy while the detailed mechanisms require further investigation." (PMID 29416846, 2018). "The reduction of PML-mediated angiostatic effects is hijacked by cancer cells to create a tumor favorable microenvironment." (PMID 29416846, 2018). "To date, nuclear PML-mediated tumor suppression function is well-documented both in vivo in mouse models and in many types of human cancer." (PMID 29416846, 2018). "We further identify an S6K/PP1α/B-Raf signaling pathway leading to activation of MAPK signaling that is antagonized by the PML tumor suppressor." (PMID 29335436, 2018). "ATO induces autophagic cell death in several types of tumor cells, and degrades PML/RARα protein via mTOR pathway-mediated autophagy in APL cells." (PMID 29362482, 2018). "More recently, further insights into the contribution of IP3R modulation in the tumor suppressive function of PML have been revealed." (PMID 28725634, 2017). "PML also regulates cell growth, stress responses and tumor suppression through a complex relationship with the mechanistic target of rapamycin (mTOR)." (PMID 28332630, 2017). "Studies using PML−/− mice have revealed PML as a tumour suppressor and regulator of retinoic acid-induced myeloid differentiation." (PMID 28317833, 2017). "Through degradation of PML, KLHL20 is expected to elicit oncogenic roles by blocking PML tumor-suppressive effects." (PMID 27200299, 2016). "ND10 nuclear bodies are also called PML oncogenic domains because of the tumor suppressor function initially identified for PML." (PMID 27048561, 2016). "Promyelocytic leukemia protein (PML) is a tumor suppressor that mainly localizes to punctate nuclear structures that are called PML nuclear bodies (PML-NBs)." (PMID 27689990, 2016). "The promyelocytic leukemia protein (PML) is a transcription factor that acts as a tumor suppressor, inhibiting proliferation and inducing cellular senescence and apoptosis through activation of the CDK inhibitor p21." (PMID 27713878, 2016). "The tumor suppressor PML plays an essential role in the regulation of CML stem cell, and various reviews have been published on this topic." (PMID 27184141, 2016). "Overall, these data demonstrate that PML/RARA impairs PTEN tumor suppressive functions by promoting the transcriptional repression of the PTEN gene and also increasing its degradation." (PMID 27626703, 2016). "While the mechanism of PML tumor suppressive functions in CML are highly complex, it should be noted that PML is a targetable tumor suppressor due to the ability of arsenic trioxide to promote its degradation." (PMID 27184141, 2016). "Since DAPK and PML both act as tumor suppressors, the ability of KLHL39 to prevent their degradation predicts a similar function of KLHL39." (PMID 27042198, 2016).
tumor (continued). "The PML protein is essential for the formation of PML-nuclear bodies and elicits pleiotropic anti-tumor effects, such as suppression of proliferation, neoangiogenesis, cell migration, and promotion of apoptosis and senescence." (PMID 27042198, 2016). "ER3 sample presented just one copy of PML per cell, indicating a deletion of this gene in this specific tumor sample." (PMID 26620706, 2015). "RT-PCR analysis was performed to determine the expression of cyclin D1 mRNA in various tumor, PML and normal samples." (PMID 25645517, 2015). "Here, we review the literature and highlight recent progress with a focus on our current understanding of the role of PML in tumor suppression." (PMID 26539288, 2015). "In this study, we demonstrated that arsenic trioxide (As2O3) effectively disrupted GSCs and inhibited tumor growth in the GSC-derived orthotopic xenografts by targeting the promyelocytic leukaemia (PML)." (PMID 26510911, 2015). "As As2O3 treatment in vivo inhibited GSC tumor growth, we further examined the effect of As2O3 on PML protein and apoptosis in GSC-derived xenografts." (PMID 26510911, 2015). "In this review, we discuss the role of PML in multiple tumor suppression pathways and summarize the players and stimuli that control PML protein expression or subcellular distribution." (PMID 26539288, 2015). "In that subtype of AML, treatment with all-trans-retinoic acid (ATRA) and ATO results in degradation of the PML-RARα fusion oncogene, differentiation of tumor cells, and apoptosis in leukemic blasts." (PMID 25628765, 2015). "Cytoplasmic PML has been reported to have both oncogenic and tumor suppressive functions in different biological contexts." (PMID 26539288, 2015). "Together, these reports conclude that cytoplasmic PML regulates the TGFβ pathway to promote its tumor suppressor activity." (PMID 26539288, 2015). "This specific assembly of E4-ORF3 creates avidity-driven interactions that capture PML as well as other tumor suppressors thus disrupting PML bodies." (PMID 25412268, 2014). "The first substrate of SENP5 identified was the tumor suppressor, PML, which has an essential role in the regulation of cell proliferation." (PMID 24926368, 2014). "Therefore, PML and PML NBs are implicated in a wide variety of cellular functions such as transcriptional regulation, protein storage, posttranslational modification, DNA damage response, apoptosis, senescence, angiogenesis, metabolism, antiviral defense and tumor suppression." (PMID 25419843, 2014). "In Prkar1a+/− tumor cells, IF analysis demonstrated that β-catenin exhibited strong co-localization with PML in tumor cells." (PMID 25299576, 2014). "The regulation of metabolism by PML further complicates our simplistic perception of PML as a “good guy”: the tumor suppressor for any stressful cellular condition." (PMID 24575390, 2014). "Using this model, we demonstrated that the CMP develop into APL by transducing PML-RARA whereas the resultant CD34− APL cells had the ability to maintain the tumor." (PMID 25369030, 2014). "There are numerous reports describing PML as a tumor suppressor, with respect to its function in mediating programmed cell death." (PMID 24728382, 2014). "The most important evidence that attests the role of PML as a tumor suppressor comes from the analysis of various genetic mouse models and human cancer samples." (PMID 23761861, 2013). "Aim of this section is to examine the main tumor suppressive pathways and factors that are engaged by PML." (PMID 23847764, 2013).
tumor (continued). "In this study, we showed that the enhanced HLA class I expression in EBV+ cHL is positively associated with the number of PML-NBs and inversely correlated with the nuclear staining intensity and the percentage of SATB1 positive tumor cells." (PMID 24009715, 2013). "Definitely, PML mediates apoptosis and senescence, two very important strategies for limiting tumor development and progression." (PMID 23847764, 2013). "The tumor suppressor promyelocytic leukemia (PML) was first identified as a fusion partner of human retinoic acid receptor alpha (RARα) as the result of a chromosomal translocation discovered in acute PML (APL)." (PMID 23504288, 2013). "Is it possible that PML, in specific contexts (e.g., origin of tumor cell, microenvironments, or metabolic states) can provide a selective pro-survival benefit?" (PMID 23936764, 2013). "These “therapeutic” effects establish a correlation between PML-NB assembly and tumor suppression, yet formal evidence that PML-NBs per se are responsible for tumor suppression is still missing." (PMID 23847764, 2013). "PML can act as a classical tumor suppressor in many cancers, but in some cases can facilitate cancer cell survival." (PMID 23936764, 2013). "In contrast to its usual perception as a classical tumor suppressor, below we will review the latest reports unveiling a potentially more sinister role for PML in cancer." (PMID 23936764, 2013). "Surprisingly, cytoplasmic PML mutants, with aberrant nuclear localization signal, function as a dominant negative, oncogenic forms of the tumor suppressor." (PMID 23936764, 2013). "Emerging studies reveal that proteasome-dependent degradation is a mechanism by which tumor cells restrict PML expression." (PMID 23734343, 2013). "The first criteria we have examined to assess if PML is a tumor suppressor is the presence of genetic alterations or abnormal expression in human cancers." (PMID 23847764, 2013). "In this context, treatment with retinoic acid and arsenic, two agents that induce disease-remission in APL patients, leads to PML-RARA degradation, cell differentiation, re-assembly of PML-NBs, and tumor regression." (PMID 23847764, 2013). "In most of these studies, PML is regarded as a tumor suppressor, a notion on the whole accepted by the scientific community." (PMID 23847764, 2013). "COL4A3 has suppressed expression in COPD, and is tied by the CLR algorithm to the transcription factors PML (also a tumor suppressor) and PITX2." (PMID 22829758, 2012). "Further work in other telomerase positive cell lines (multiple clones) and tumours will help to clarify of the role of PML in influencing the existing telomerase pathway." (PMID 22925423, 2012). "PML is known as a tumor suppressor, and indeed, we identified Pathways in cancer as the second largest affected category of genes (n=39) following its knockdown." (PMID 22947142, 2012). "The PML/RARα oncogenic fusion protein is directly responsible for the silencing of the tumor suppressors let-7c and miR-342." (PMID 24278756, 2012). "PML is a well-defined tumor suppressor; however its role in diseases other than cancers has yet to be determined." (PMID 22947142, 2012). "It would be interesting to study if there is a correlation between PML expression and telomerase levels and activity in cancer tumours." (PMID 22925423, 2012). "However, it remains to be established whether loss of the tumor suppressor PML contributes to changes in the host immune response or the tumor microenvironment, perhaps resulting in either immunosurveillance or immune escape, by modulation of transcription factors." (PMID 22022583, 2011).
tumor (continued). "The PML tumor suppressor is the founding component of the multiprotein nuclear structures known as PML nuclear bodies (PML-NBs), which control several cellular functions including apoptosis and antiviral effects." (PMID 21305000, 2011). "The same group have also identified HAUSP as a critical and essential enzyme for PTEN deubiquitination and nuclear exclusion, a mechanism which involved also the tumour-suppressor PML." (PMID 21904669, 2011). "Herein, we investigated the relationship between the extent of tumor-infiltrating lymphocytes and the status of PML protein expression in advanced gastric carcinoma." (PMID 22022583, 2011). "We here show that PML protein expression in tumor cells is inversely correlated with the extent of infiltration of CD8+ T-cells into tumor tissues." (PMID 22022583, 2011). "The promyelocytic leukemia protein (PML) is a tumor suppressor critical for formation of nuclear bodies (NBs) performing important functions in transcription, apoptosis, DNA repair and antiviral responses." (PMID 21998700, 2011). "In the present study, we examined PML function with respect to recruitment of lymphocytes and modulation of the expression of tumor-derived factors." (PMID 22022583, 2011). "Although PML protein expression was reduced or abolished in tumor cells, all of normal gastric mucosal glands, stromal tissues, and lymphoid cells, exhibited diffuse moderate-to-strong nuclear immunopositivity for PML." (PMID 22022583, 2011). "Nuclei of normal gastric mucosal glands, stromal tissues, and lymphoid cells were diffusely immunopositive (moderate-to-strong) for PML protein expression, whereas PML levels were reduced or abolished in tumor cells." (PMID 22022583, 2011). "Representative examples of variations in PML protein status that correlated with different IP-10 expression levels in tumor cells from advanced gastric carcinomas are shown (right)." (PMID 22022583, 2011). "The tumor suppressor PML is the only RBCC/TRIM family member of which we are aware for which cancer-specific mutations have been observed." (PMID 19536326, 2009). "Mutations in PTEN, PML, TSC, and VHL have been identified in tumor cells that result in the deregulation of HIF via multiple distinct mechanisms involving Akt/PI3K, mTOR and the ubiquitin pathway." (PMID 18773095, 2008). "PML is a multifunctional protein described as a tumour suppressor with antiviral properties." (PMID 41597397, 2026). "Mechanistically, the loss of PML increases STAT1 binding to the CXCL10 promoter, likely associated with a PML-regulated region on the promoter, thus upregulating CXCL10 expression in tumor cells and aiding the infiltration of immune cells." (PMID 40909948, 2025). "Since PML functions as a tumor suppressor, disruption of PML NBs by IKKε may also contribute to KSHV-associated tumorigenesis." (PMID 39823515, 2025). "The combination treatment selectively suppressed the tumor growth of PML-intact cells." (PMID 40753178, 2025). "For example, the results of recent research indicate that histone lactylation improves ALKBH3 expression and simultaneously attenuates the formation of tumor-suppressive promyelocytic leukemia protein (PML) condensates by removing the m1A methylation of SP100A." (PMID 40672754, 2025). "To assess whether the cytotoxic effects of the combined drug treatment are dependent on PML in vivo, we established tumor-bearing nude mice using either control or PML gene-edited MOLM-13 cells and administered CDK4/6i and ATRA." (PMID 40753178, 2025).